TNF (tumor necrosis factor)
Diseases named in the same sentence as TNF in open-access papers (continued):
Sharing a sentence is not in itself a finding about the gene and the disease.
psoriasis (continued). "We identified 40 articles with 106 cases of new-onset TNF-α inhibitor-induced psoriasis." (PMID 37664349, 2023). "Furthermore, dendritic cells produce TNF-α, a central molecule in the inflammatory milieu of psoriasis, which directly affects keratinocyte gene expression." (PMID 36754913, 2023). "The authors found that the repetitive application of ItP of TNF-α drug etanercept (recombinant human TNF-α receptor: Fc fusion protein) on imiquimod (IMQ)-induced psoriasis skin significantly reduced the pathogenesis of psoriasis." (PMID 38140019, 2023). "In addition to keratinocytes, macrophages, neutrophils, lymphocytes, and mast cells produce high levels of cytokines such as TNF-α, IL-1β, and IL-6 to maintain the positive feedback cycle in psoriasis." (PMID 37585684, 2023). "Interestingly, TNFα, INFγ and IL-17A, which are the main effectors of the Th1/Th17 response in psoriasis pathogenesis, were also found to stimulate the release of IL-33." (PMID 37509136, 2023). "The clinical heterogeneity regarding the response profile of the antitumor necrosis factor (anti-TNF) in patients with Crohn’s disease (CD) and psoriasis (PsO) is attributed, amongst others, to genetic factors that influence the regulatory mechanisms which orchestrate the inflammatory response." (PMID 36833372, 2023). "For psoriasis, the scRNA-seq analysis has identified an aberrant inflammatory transcription of A20 in KCs of psoriasis, that is related to the IL-17 and TNF-α signaling pathways and may have potential for targeted therapy." (PMID 37270497, 2023). "However, paradoxical reactions, including paradoxical psoriasis and arthritis, have been reported in axSpA patients receiving TNF-α inhibitors." (PMID 38111814, 2023). "Recently, aleosin, an active constituent of AV, was found to reduce leucocytes adherence and TNF-a level, which is a major triggering factor of psoriasis pathogenesis by stimulating keratinocyte proliferation and increasing migration and adhesion of macrophages and lymphocytes." (PMID 36986611, 2023). "One of the biggest breakthroughs in the treatment of psoriasis and psoriatic arthritis was the introduction of biologic agents (like TNF-α inhibitors, inhibitors of the IL-17 pathway, inhibitors of IL-23, and related cytokines) and Janus kinase (JAK) inhibitors." (PMID 38276003, 2023). "Higher succinate and TNF levels in the colon have also been reported in human psoriasis." (PMID 37894934, 2023). "TNF-α inhibitors were the first biologic drugs available for psoriasis treatment." (PMID 37372997, 2023). "Our purpose was to elucidate the real-world incidences of adverse events of interest, including new-onset IBD, oral/GI candidiasis, pulmonary tuberculosis, herpes zoster, and major cardiovascular events (MACEs) in patients with psoriasis treated using TNF-α, IL-12/23, IL-17, and IL-23 inhibitors." (PMID 38137722, 2023). "Psoriasis is currently regarded as a systemic low-grade inflammation supported by a variety of cytokines, chemokines, and other inflammatory mediators including tumor necrosis factor (TNF)-α, interferon (IFN)-γ, interleukin (IL)-17, IL-22, IL-23, and IL-1β." (PMID 37049545, 2023). "On the other hand, TNF-α has been shown to inhibit adiponectin production, which may be one of the factors for reduced adiponectin levels in patients with psoriasis." (PMID 36675592, 2023). "Our study showed that the use of IL-17i and IL-23i was a protective factor for psoriasis compared with TNF-αi, and could keep the psoriasis stable." (PMID 38020100, 2023). "Anti-TNFα is a mainstream therapy in certain autoimmune conditions (e.g., IBD and psoriasis); however, it may be associated with increased susceptibility to infections and a lower vaccine response." (PMID 37047412, 2023). "TNF-α and IL-17A act in a synergic manner to maintain the cytokine cascade in psoriasis." (PMID 38003284, 2023).
psoriasis (continued). "In all patients, the percentage reductions of the PLR and CRP were positively correlated with that of the PASI at week 52, indicating that the PLR and CRP might act as biomarkers reflecting treatment response to TNF-α inhibitors in psoriasis." (PMID 36769622, 2023). "The childhood genes were MIR-1914, MIR-647 and MAP3K8 (common wart) and TNF (psoriasis)." (PMID 37697338, 2023). "The Th17 cells produce IL-6, IL-17, and TNF-α to mediate the inflammatory reaction in psoriasis." (PMID 37596509, 2023). "TNF-α inhibitors or monoclonal antibodies have been proven effective in treating psoriasis." (PMID 37465147, 2023). "Psoriasis is an inflammatory condition that is associated with excessive secretion of proinflammatory cytokines (IL-2, IL-6, IL-8, IL-12, IL-19, IL-22, IL-23, IFN-γ and TNF-α) into blood as well as dermal tissue." (PMID 37266425, 2023). "TNF has a significant function in the induction and transmission of immunological activity by focusing on an inflammatory response that penetrates the epidermis, and it is present in high amounts in lesions on the skin and plasma of psoriasis patients." (PMID 37965393, 2023). "This study demonstrated that BAC might act as an inhibitor of STAT3 in psoriasis to inhibit STAT3 phosphorylation in TNF-α-induced HaCaT cells to regulate the proliferation and expression of inflammatory cytokines." (PMID 37298949, 2023). "To better understand the non-responsiveness in psoriasis, we aimed to uncover the molecular architecture that underlies the responsiveness to biological drugs, focusing on anti-TNF and anti-IL12/IL23, by using GO on the set of previously published biomarkers." (PMID 37631238, 2023). "Furthermore, TNF and mTOR signaling pathways, which play a role in the pathogenesis of psoriasis, were among the major disease-residual pathways identified in our STRING and KEGG pathway analyses." (PMID 36901987, 2023). "TNF-α/NF-κB pathway is another important inflammatory pathway in the development of psoriasis." (PMID 38007430, 2023). "In psoriasis, the key target of TNF-α is the NF-κB signaling pathway." (PMID 36839031, 2023). "In recent years, biological agents (e.g. TNFα inhibitors, IL-23 inhibitors, IL-17 inhibitors, and IL-12/23 inhibitors) have become important treatments for patients with moderate to severe psoriasis, which block the proinflammatory cytokines and lymphocyte activation in psoriasis." (PMID 36890558, 2023). "The CRP and PLR might act as biomarkers reflecting the treatment response to TNF-α inhibitors in patients with psoriasis." (PMID 36769622, 2023). "Tofacitinib was the only non-TNF monotherapy that was not statistically significantly associated with psoriasis within the 95% CI." (PMID 37369753, 2023). "Skin tissue RT-PCR detection determined that the IMQ + PBS groups in all three psoriasis mouse models had significantly increased TNF-α, IL-1, IL-6, IL-12, IFN-α, IFN-β, IFN-γ, G-CSF, GM-CSF, IL-36α, IL-36β, and IL-36γ gene expression compared to the NC groups." (PMID 37160878, 2023). "Biological therapies that target tumor necrosis factor α (TNFα), interleukin (IL)-12/IL-23 p40, IL-23p19, IL-17A, and IL-36R are increasingly used for patients with moderate to severe, refractory, and special types of psoriasis." (PMID 38196435, 2023). "We, and others, have shown that psoriasis induction in mice leads to the higher production of succinate by the gut microbiota, which induces the proliferation of resident colonic macrophages and increased levels of TNF in the gut." (PMID 37894934, 2023). "Interaction of S100A7 with RAGE activates p38 MAPK (mitogen-activated protein kinase) and ERK (extracellular signal-regulated kinase) signaling pathways, leading to production of multiple inflammatory mediators involved in psoriasis, including IL-1α, IL-1β, IL-6, IL-8, TNF-α." (PMID 37346040, 2023).
psoriasis (continued). "Taken together, it tends to suggest that the intake of linoleic acid may have therapeutic efficacy against cellular autoimmune disorders, especially type 1 immune response characterized by overproduction of IFN-γ and TNF-α, e.g. in psoriasis." (PMID 37492568, 2023). "TNFα is a proinflammatory cytokine that is critical for host defense and is clinically relevant to several barrier tissue chronic inflammatory diseases including psoriasis and inflammatory bowel disease (IBD)." (PMID 36591258, 2022). "The risk of psoriasis in anti-TNF-treated patients was not different according to either IBD types (UC or CD) or anti-TNF agent types (infliximab, adalimumab, or certolizumab)." (PMID 35801760, 2022). "TNF-α is involved in the pathogenesis of osteoporosis in psoriasis." (PMID 35457278, 2022). "Because contact cell-mediated allergy and psoriasis are T-cell-mediated, involving Th1 and Th17 lymphocytes, and TNF-α, IL-17, and IL-23 are cytokine mediators in their pathogeneses, some authors have assessed the skin patch testing in patients with psoriasis treated with biologics." (PMID 35888633, 2022). "Tumor necrosis factor-α (TNF-α) inhibitors are widely used to treat patients with psoriasis." (PMID 35744043, 2022). "Research shows that adipokines, both leptin and resistin, which enhance the production of proinflammatory cytokines (e.g., TNF-α), may be involved in the pathogenesis of psoriasis." (PMID 35330186, 2022). "Indeed, a prospective study evaluating CFR in 37 consecutive patients with moderate to severe psoriasis before and after 6 months of treatment with TNF-α inhibitors reported a CFR increase from 2.2 ± 0.7 to 3.02 ± 0.8 (p<0.0001)." (PMID 35686132, 2022). "However, clinical trials demonstrated the heterogeneous response of psoriasis patients to anti-TNF-α treatments, thus stimulating the search for novel therapeutical targets." (PMID 36364420, 2022). "Moreover, detailed information on the duration of anti-TNF treatment, the time gap between the initiation of anti-TNF treatment and psoriasis development, dose of anti-TNF agents, and combination therapy with immunosuppressants was not available." (PMID 35801760, 2022). "Notably, psoriasis is mediated by T-cell effector cytokines, including IL-17A, IL-22, and TNF-α, which induce antimicrobial peptides in keratinocytes and neutrophils." (PMID 36232814, 2022). "In the case of psoriasis, a prototypical TNFα–Th17 disease model, recent data demonstrated increased sodium and water retention in lesional and non-lesional skin, but only in patients with a moderate to severe form of the disease (PASI > 5), and not in those with a mild form (PASI < 5)." (PMID 35883760, 2022). "Psoriasis development between anti-TNF-treated and anti-TNF-naïve patients was compared." (PMID 35801760, 2022). "Generally, a similar efficacy in elderly patients undergoing anti-TNF has been reported so far when compared with younger patients, but a few studies show a lower response rate in elderly patients that were treated for other diseases than psoriasis." (PMID 36359399, 2022). "Similarly, several studies have consistently reported that the serum levels of TNF-α are significantly increased in patients with psoriasis compared to healthy controls." (PMID 36012327, 2022). "The pathogenesis of psoriasis is closely related to the expression of TNF-α." (PMID 35330186, 2022). "Moreover, subclinical left and right ventricular myocardial dysfunctions have demonstrated to be ameliorated following anti TNF-α therapy in patients with severe psoriasis." (PMID 35686132, 2022). "Psoriasis is a chronic inflammatory disease mediated by the TNF-α proinflammatory cytokine." (PMID 35805960, 2022). "Inflammatory cytokines, including IL-22, IL-17, TNF-α can induce the aberrant activation of mTOR cascade in keratinocytes, leading to enhanced keratinocyte proliferation and reduced differentiation, which are the hallmarks of psoriasis." (PMID 35938153, 2022).
psoriasis (continued). "Besides INF-γ and TNF-α, some key cytokines of interleukin family have been also identified as the key factors in the pathogenesis of psoriasis." (PMID 36618400, 2022). "However, a detailed characterization of the immune phenotype of TNF-α inhibitor-induced psoriasiform and eczematous eruptions revealed that these lesions were immunologically different from those found in conventional psoriasis and eczema." (PMID 35884790, 2022). "Since prominent epidermal hyperplasia is thought to result from the interaction between keratinocytes and a complex cytokine network due to abnormal T-cell regulation, many effective therapies targeting TNF-α, IL-23, or IL-17 have been developed and used to treat patients with psoriasis." (PMID 35163233, 2022). "Previous studies have also shown the safety of dose tapering other TNFα inhibitors in psoriasis." (PMID 36004912, 2022). "TNF-α inhibitors, a type of immunomodulator, has also been reported to alleviate fatigue symptoms in some autoimmune diseases and attenuate CFS risk in patients with psoriasis." (PMID 35189895, 2022). "INF-γ- and TNF-α-mediated inflammatory signaling is the key process in psoriasis." (PMID 35163689, 2022). "The current study might be the first meta-analysis of the comparison of psoriasis development in anti-TNF-treated and anti-TNF-naïve patients with IBD, although there have been many studies supporting a positive relationship between psoriasis and IBD." (PMID 35801760, 2022). "Besides, Etanercept is a monoclonal antibody targeted against TNF-α, which has been approved for the treatment of RA, juvenile RA, AS, psoriasis, and PsA." (PMID 36119071, 2022). "TNF-alpha inhibitors were the first biologic agents to be approved in the treatment of psoriasis." (PMID 35741329, 2022). "TNF-α inhibitors were introduced more than 20 years ago and are being used for an expanding number of rheumatic and autoimmune diseases, such as RA, inflammatory bowel disease (ulcerative colitis and Crohn’s disease), psoriasis, and ankylosing spondylitis." (PMID 35884790, 2022). "Post-anti-TNF psoriasis risk was not significantly different between CD and UC patients (RR = 1.30, 95% CI = 0.87-1.95; the higher the RR, the higher the likelihood of developing psoriasis in CD patients than in UC patients)." (PMID 35801760, 2022). "Indeed, treatment with TNF-α inhibitors has been reported to induce eosinophilia in psoriasis patients, suggesting that they revert to a Th2 phenotype." (PMID 35884790, 2022). "Psoriasis alone can affect mental health; however, systemic inflammation through TNF may have an adverse effect on neurocognitive functions." (PMID 35743091, 2022). "However, the advent of biological medicines that target the critical immune pathways involved in the etiopathogenesis of psoriasis, such as IL-17, IL-23, and Tumor Necrosis Factor (TNF), has changed the therapeutic landscape for severe forms of psoriasis." (PMID 35637050, 2022). "Anti-psoriatic therapies include topical treatment with glucocorticoids or retinoids and systemic treatment such as methotrexate, cyclosporine, corticosteroids, fumarate and several biologics targeting the key players in psoriasis (TNFα, IL-17 and IL-23) or their signaling pathways." (PMID 35812457, 2022). "Both psoriasis and IBD are associated with T-cell activation and production of proinflammatory cytokines, such as IL-17A, IL-23, and TNF-α, but biologics targeting IL-17A, IL-23, or TNF-α showed different therapeutic effects in psoriasis or IBD patients." (PMID 35801760, 2022). "However, in combination with IL-17A and other cytokines, TNF-α is a significant element of the cytokine milieu in psoriasis." (PMID 35313642, 2022). "This phenomenon may be explained by the elevated serum TNF-α levels observed in patients with chronic hepatitis, which leads to insulin resistance and, consequently, diabetes, hypertension, and, possibly, psoriasis." (PMID 35805960, 2022).
psoriasis (continued). "In addition, SPRR2C, a potential regulator that modulates IL-22 stimulation, was upregulated in both atopic dermatitis and psoriasis lesional skin and was also downstream of the IL-17A and IL-17 + TNF signaling in keratinocytes." (PMID 35559048, 2022). "In addition, secoligulene downregulated the expression of chemokines such as CXCL8 and CCL20 in the TNF-α/IL-17/IFN-γ induced HaCaT psoriasis model." (PMID 36015080, 2022). "The Th1 (TNF-α) and Th17 (IL-17A and IL-22)-related cytokines are important proinflammatory cytokines, involved in maintenance of chronic inflammatory response and epithelial tissues remodeling in psoriasis pathogenesis." (PMID 36741386, 2022). "In addition to TNF-α and IL-17, many new psoriasis drug targets came into place since 2018 (IL-12/23) and 2019 (IL-36 and glucagon-like peptide-1 (GLP-1))." (PMID 35529441, 2022). "In an article published in 2013, researchers explored the impact of autoimmune diseases (particularly rheumatoid arthritis, psoriasis, and systemic sclerosis) and anti-TNF-α therapy on the clinical and immunological periodontal parameters of diseased subjects and systemically healthy controls." (PMID 35454992, 2022). "TNF-α is another cytokine up-regulated in psoriasis patients." (PMID 36618400, 2022). "In addition, TNF-α was described as a pivotal cytokine that is involved in the pathophysiology of psoriasis and also as a mediator of focal infection in skin lesions." (PMID 36501011, 2022). "Th1/17 cells are the main source of psoriasis cytokines IL-17, 22, TNF-α and interferon-γ." (PMID 36385768, 2022). "The current work demonstrated that the fabricated gelatin patch presented suitable morphology (the size of nanofiber and porous structure) to support the topical release of anti-TNFα and anti-IL-17α suggesting future developments to adapt their application for the treatment of psoriasis." (PMID 35742957, 2022). "Data on TNF-α blockers suggest that they are safe and effective in managing pediatric psoriasis." (PMID 36232430, 2022). "It binds and neutralizes TNF, one of the key proinflammatory cytokines in psoriasis." (PMID 35327421, 2022). "The increased number of myeloid dendritic cells (mDCs) in psoriasis may drive the immunopathological process by releasing IL-8 and TNFα and promoting T-cell proliferation in response to oxidative stress." (PMID 35163855, 2022). "Moreover, AEC-SC can also suppress the expression of other inflammatory factors IL-6 and TNFα, which are important for maintaining the inflammatory environment of psoriasis." (PMID 35922852, 2022). "Cytokines involved in the pathogenesis of psoriasis include IL-17, IL-22, IL-23, TNFα, etc." (PMID 35330444, 2022). "IL17 and IL23, as well as TNF, are known to be involved in the pathogenesis of psoriasis." (PMID 36699407, 2022). "The overall pooled incidence of psoriasis and/or psoriasiform lesions following anti-TNF therapy was 6.0% (5.0-7.0%; I2 = 93.9%), with 6.9% (5.1-8.7%; I2 = 92.4%) for psoriasiform lesions and 4.6% (3.6-5.6%; I2 = 93.9%) for psoriasis." (PMID 35300336, 2022). "In line, new treatment options for PSO, such as systemic therapy, acting as inhibitors for certain pro-inflammatory cytokines [e.g., secukinumab as interleukin(IL)-17 inhibitor], or biologics, acting as TNF-α inhibitors, are effective treatment options for moderate-to-severe psoriasis forms." (PMID 35546938, 2022). "Furthermore, 3 patients with psoriasis reportedly developed CIDP after receiving treatment for anti-tumor necrosis factor alpha (TNF-α)." (PMID 36324078, 2022). "Elevated anti-TNF-α antibody was once reported in psoriasis." (PMID 36118416, 2022). "Because inflammatory cytokines, i.e., TNF-α, IL-17, and IL-23, are involved in the pathogenesis of psoriasis, the high safety profile of DXM and its general immunomodulatory effects are advantages in its clinical application as a potential therapeutic treatment for psoriasis." (PMID 35629363, 2022).